TUBA3FP (tubulin alpha 3f pseudogene)
Gene: Protein-coding gene on chromosome 22 (21,008,193 to 21,014,292, reverse strand). Ensembl gene ENSG00000284130.
Diseases named in the same sentence as TUBA3FP in open-access papers:
TUBA3FP is named in the same sentence as 1 disease in open-access papers, as found by Europe PMC text mining. Sharing a sentence is not in itself a finding about the gene and the disease. The quoted sentences say what the papers report.
cancer (2 papers, 2017 to 2022). A tumor composed of atypical neoplastic, often pleomorphic cells that invade other tissues. "Except for 3 pseudogenes (GUCY1B2, HNRNPA1P33, and TUBA3FP), all of the remaining 15 genes showed the most involvement as tumor suppressor genes in distinct carcinomas, and four genes (TUBGCP2, PLEC, CLEC11A, and BARD1) were associated with AML." (PMID 29299160, 2017). "The risk signature of our study included 8 lncRNAs (CRNDE, LINC00844, FAM66C, TUBA3FP, SNHG8, HAR1A, LINC00641, and MYCNOS), and previous evidence has suggested that these lncRNAs are closely linked to the occurrence and development of cancer." (PMID 35832170, 2022).